SNORA28 (small nucleolar RNA, H/ACA box 28)
Synonyms: ACA28
Gene: Small nucleolar RNA gene on chromosome 14 (103,337,849 to 103,337,974, forward strand). Ensembl gene ENSG00000272533.
Gene Ontology:
Biological process: RNA processing
Cellular component: nucleolus
Homologues: Orthologues: chimpanzee SNORA28 (100% identical), macaque SNORA28 (98% identical), pig SNORA28 (95% identical), rabbit SNORA28 (94% identical), mouse Snora28 (94% identical), rat Snora28 (90% identical), rat LOC120101244 (89% identical), guinea pig SNORA28 (87% identical), rat LOC120096389 (71% identical).
Diseases named in the same sentence as SNORA28 in open-access papers:
SNORA28 is named in the same sentence as 6 diseases in open-access papers, as found by Europe PMC text mining. Sharing a sentence is not in itself a finding about the gene and the disease. The quoted sentences say what the papers report.
tumor (2 papers, 2020 to 2024). "In the present study, we found that SNORA28 regulates the growth of CRC cells and enhances their radioresistance, implying that snoRNAs directly regulate the radiosensitivity of tumor cells." (PMID 38924373, 2024). "Thus, our results shed light on the expression pattern and biological function of SNORA28 in CRC, in addition to providing insights into how snoRNAs may regulate tumor cell radiosensitivity, which highlights their potential as radiosensitizing targets." (PMID 38924373, 2024).
SNORA28 also shares sentences with these, for which no sentence is quoted: cancer (1 paper); colorectal cancer (1); melanoma (1); osteosarcoma (1); Pancreatic Cancer (1).